ZP4 (zona pellucida glycoprotein 4)
Description:
Component of the zona pellucida, an extracellular matrix surrounding oocytes which mediates sperm binding, induction of the acrosome reaction and prevents post-fertilization polyspermy. The zona pellucida is composed of 3 to 4 glycoproteins, ZP1, ZP2, ZP3, and ZP4. ZP4 may act as a sperm receptor.
Synonyms: Zp-4; ZPB; ZPB2; ZP1B; ZBP; ZP1
Tractability: Antibody: its Gene Ontology location is reachable by antibodies, with high confidence; UniProt places it where antibodies can reach, with medium confidence; UniProt predicts a signal peptide or a membrane-spanning region.
Gene: Protein-coding gene on chromosome 1 (237,877,864 to 237,890,922, reverse strand). Ensembl gene ENSG00000116996.
Subcellular location: Zona pellucida (Processed zona pellucida sperm-binding protein 4); Cell membrane
Pathways (Reactome):
Reproduction: Interaction With Cumulus Cells And The Zona Pellucida
Gene Ontology:
Molecular function: acrosin binding; identical protein binding; protein binding; structural constituent of egg coat
Biological process: acrosomal vesicle exocytosis; negative regulation of binding of sperm to zona pellucida; positive regulation of acrosome reaction; positive regulation of humoral immune response; positive regulation of T cell proliferation; binding of sperm to zona pellucida; prevention of polyspermy
Cellular component: egg coat; extracellular region; plasma membrane
Genetic constraint (gnomAD): Loss-of-function variants: 63 observed, 66.21 expected, observed/expected ratio (o/e) 0.95, 90% interval 0.78 to 1.17. The upper end of that interval is the gene's LOEUF score, 1.17, which puts it in group 5 of 6, group 1 being the genes least tolerant of losing a copy. Missense variants: 774 observed, 688.2 expected, observed/expected ratio (o/e) 1.12, 90% interval 1.06 to 1.19. Synonymous variants: 289 observed, 259.42 expected, observed/expected ratio (o/e) 1.11, 90% interval 1.01 to 1.23.
Homologues: Orthologues: chimpanzee ZP4 (96% identical), macaque ZP4 (92% identical), rabbit ZP4 (69% identical), dog ZP4 (68% identical), pig ZP4 (67% identical), rat Zp4 (64% identical), tropical clawed frog zp4 (40% identical), tropical clawed frog zp4.2 (35% identical), tropical clawed frog zp4.2 (23% identical), zebrafish zmp:0000001145 (18% identical). Paralogues in human: ZP1 (36% identical), ZP2 (29% identical), QRICH2 (13% identical), C16orf96 (11% identical).
Diseases named in the same sentence as ZP4 in open-access papers:
ZP4 is named in the same sentence as 11 diseases in open-access papers, as found by Europe PMC text mining. Sharing a sentence is not in itself a finding about the gene and the disease. The quoted sentences say what the papers report.
primary open angle glaucoma (6 papers, 2012 to 2022). "ZP4 plays a role in fertilization and preimplantation development; and genetic variations in ZP4 are reported to be associated with ovarian disease and glaucoma." (PMID 31337432, 2019). "Our study was unable to replicate the previously reported association for variant rs547984 flanking the ZP4 gene with POAG and glaucoma specific indices such as IOP and cup/disc ratio indicating that this SNP is not a risk factor for POAG in the Saudi cohort." (PMID 28648143, 2017).
Infertility (4 papers, 2015 to 2022). "Three primary infertile women with ZP4 mutations were reported in the literature, aged from 33 to 34 years old, with a history of infertility of 3 to 5 years." (PMID 36476320, 2022). "Mutations in ZP1-3 genes have been recently associated with women infertility but the association between these PTC mutations in ZP4 and woman infertility remains to be explored." (PMID 31635692, 2019). "This protective function was severely impaired following ZP4 ablation, ultimately causing embryonic death and infertility." (PMID 31635692, 2019). "In order to determine whether ZP4 deficiency could lead to infertility in women, we searched for loss-of-function mutations in the Genome Aggregation Database, which includes data from 141456 individuals." (PMID 31635692, 2019). "In some patients with PCOS and infertility, ZP4 mutation can be found." (PMID 25740067, 2015). "The presence of ZP4 gene mutation in one case of PCOS is not sufficient to judge about its role in the pathogenesis of PCOS or infertility." (PMID 25740067, 2015).
female infertility (3 papers, 2019 to 2023). Diminished or absent ability of a female to achieve conception. "In this sense, these results highlight ZP4 mutations as a possible cause for female infertility in both humans and livestock or wild species, and pave the way for the development of contraceptive methods based on ZP4 disruption." (PMID 31635692, 2019). "Mutations in ZP4 are associated with abnormal zona pellucida and with female infertility." (PMID 35456401, 2022). "Studies have reported that the variants in ZP1(MIM: 195000), ZP2 (MIM: 182888), and ZP3 (MIM: 182889) affect the formation of zona pellucida and result in female infertility, but there is no convincing evidence to prove that ZP4 (MIM: 613514) variant responsible for female infertility." (PMID 37052235, 2023).
polycystic ovaries (2 papers, 2015 to 2025). "The expression of the zona pellucida 4 (ZP4) gene in polycystic ovaries is low compared to healthy controls, probably due to high levels of androgens that regulate the expression of zona pellucida genes." (PMID 39797326, 2025). "Regarding these findings and previous studies of other oocyte-specific genes, the aim of this study was to analyze the ZP4 coding sequence and its expression in patients with polycystic ovary syndrome." (PMID 25740067, 2015). "In the presented study, the expression of Zp4 in polycystic ovaries is not compared to healthy controls." (PMID 25740067, 2015).
breast carcinoma (1 paper, 2022). "The two proteins, ZP4 and PTCH1, could therefore potentially represent an unknown link between MHT usage, female tissues, and mammographic breast density all leading to increased risk of breast cancer." (PMID 35033985, 2022).
colon cancer (1 paper, 2021). "In contrast, ZP1, ZP3, and ZP4 were not detectable at all or only in a small number of colon cancer specimens." (PMID 33917056, 2021).
cancer (1 paper, 2024). A tumor composed of atypical neoplastic, often pleomorphic cells that invade other tissues. "The list of 78 also included five encoding membrane proteins, namely SLCO6A1, ZP4, OR2C3, OR1N1, and OR4N2, which are potential pan-cancer targets for CAR-T and antibody-drug conjugates." (PMID 39561714, 2024).
tumor (1 paper, 2025). "Another study identified zona pellucida glycoprotein 4 (ZP4) as a novel and highly specific tumor-associated antigen for TNBC through integrative analysis of transcriptomic and proteomic datasets." (PMID 41007774, 2025).
ZP4 also shares sentences with these, for which no sentence is quoted: developmental delay (1 paper); melanoma (1); ovarian disease (1).